OR4F7P (olfactory receptor family 4 subfamily F member 7 pseudogene)
Synonyms: OR4F10
Gene: Unprocessed pseudogene on chromosome 6 (170,639,606 to 170,640,536, forward strand). Ensembl gene ENSG00000217874.
Diseases named in the same sentence as OR4F7P in open-access papers:
OR4F7P is named in the same sentence as 1 disease in open-access papers, as found by Europe PMC text mining. Sharing a sentence is not in itself a finding about the gene and the disease. The quoted sentences say what the papers report.
tumor (1 paper, 2022). "Five genes at 6q27 exhibiting large genomic changes (PSMB1, PDCD2, TBP, OR4F7P and WBP1LP8) were found in HCI-010 as the region transitioned from amplified in the human tumor to deleted in the early passage of the PDX and PDxO." (PMID 35221336, 2022).